NR1H4 (nuclear receptor subfamily 1 group H member 4)
Description:
Ligand-activated transcription factor. Receptor for bile acids (BAs) such as chenodeoxycholic acid (CDCA), lithocholic acid, deoxycholic acid (DCA) and allocholic acid (ACA). Plays a essential role in BA homeostasis through the regulation of genes involved in BA synthesis, conjugation and enterohepatic circulation. Also regulates lipid and glucose homeostasis and is involved innate immune response. The FXR-RXR heterodimer binds predominantly to farnesoid X receptor response elements (FXREs) containing two inverted repeats of the consensus sequence 5'-AGGTCA-3' in which the monomers are spaced by 1 nucleotide (IR-1) but also to tandem repeat DR1 sites with lower affinity, and can be activated by either FXR or RXR-specific ligands. It is proposed that monomeric nuclear receptors such as NR5A2/LRH-1 bound to coregulatory nuclear responsive element (NRE) halfsites located in close proximity to FXREs modulate transcriptional activity (By similarity). In the liver activates transcription of the corepressor NR0B2 thereby indirectly inhibiting CYP7A1 and CYP8B1 (involved in BA synthesis) implicating at least in part histone demethylase KDM1A resulting in epigenomic repression, and SLC10A1/NTCP (involved in hepatic uptake of conjugated BAs). Activates transcription of the repressor MAFG (involved in regulation of BA synthesis) (By similarity). Activates transcription of SLC27A5/BACS and BAAT (involved in BA conjugation), ABCB11/BSEP (involved in bile salt export) by directly recruiting histone methyltransferase CARM1, and ABCC2/MRP2 (involved in secretion of conjugated BAs) and ABCB4 (involved in secretion of phosphatidylcholine in the small intestine). Activates transcription of SLC27A5/BACS and BAAT (involved in BA conjugation), ABCB11/BSEP (involved in bile salt export) by directly recruiting histone methyltransferase CARM1, and ABCC2/MRP2 (involved in secretion of conjugated BAs) and ABCB4 (involved in secretion of phosphatidylcholine in the small intestine). In the intestine activates FGF19 expression and secretion leading to hepatic CYP7A1 repression. The function also involves the coordinated induction of hepatic KLB/beta-klotho expression (By similarity). Regulates transcription of liver UGT2B4 and SULT2A1 involved in BA detoxification; binding to the UGT2B4 promoter seems to imply a monomeric transactivation independent of RXRA. Modulates lipid homeostasis by activating liver NR0B2/SHP-mediated repression of SREBF1 (involved in de novo lipogenesis), expression of PLTP (involved in HDL formation), SCARB1 (involved in HDL hepatic uptake), APOE, APOC1, APOC4, PPARA (involved in beta-oxidation of fatty acids), VLDLR and SDC1 (involved in the hepatic uptake of LDL and IDL remnants), and inhibiting expression of MTTP (involved in VLDL assembly. Increases expression of APOC2 (promoting lipoprotein lipase activity implicated in triglyceride clearance). Transrepresses APOA1 involving a monomeric competition with NR2A1 for binding to a DR1 element. Also reduces triglyceride clearance by inhibiting expression of ANGPTL3 and APOC3 (both involved in inhibition of lipoprotein lipase). Involved in glucose homeostasis by modulating hepatic gluconeogenesis through activation of NR0B2/SHP-mediated repression of respective genes. Modulates glycogen synthesis (inducing phosphorylation of glycogen synthase kinase-3) (By similarity). Modulates glucose-stimulated insulin secretion and is involved in insulin resistance. Involved in intestinal innate immunity. Plays a role in protecting the distal small intestine against bacterial overgrowth and preservation of the epithelial barrier (By similarity). Down-regulates inflammatory cytokine expression in several types of immune cells including macrophages and mononuclear cells. Mediates trans-repression of TLR4-induced cytokine expression; the function seems to require its sumoylation and prevents N-CoR nuclear receptor corepressor clearance from target genes such as IL1B and NOS2. Involved in the TLR9-mediated protective mechanism in intestinal inflammation. Plays an anti-inflammatory role in liver inflammation; proposed to inhibit pro-inflammatory (but not antiapoptotic) NF-kappa-B signaling) (By similarity). [Isoform 1]: Promotes transcriptional activation of target genes NR0B2/SHP (inducible by unconjugated CDCA), SLC51B/OSTB (inducible by unconjugated CDCA and DCA) and FABP6/IBAP; low activity for ABCB11/BSEP (inducible by unconjugated CDCA, DCA and ACA); not inducible by taurine- and glycine-amidated CDCA. [Isoform 2]: Promotes transcriptional activation of target genes ABCB11/BSEP (inducible by unconjugated CDCA, DCA and ACA), NR0B2/SHP (inducible by unconjugated CDCA DCA and ACA), SLC51B/OSTB (inducible by unconjugated CDCA and DCA) and FABP6/IBAP; not inducible by taurine- and glycine-amidated CDCA. [Isoform 3]: Promotes transcriptional activation of target genes NR0B2/SHP (inducible by unconjugated CDCA), SLC51B/OSTB (inducible by unconjugated CDCA and DCA) and IBAP; low activity for ABCB11/BSEP (inducible by unconjugated CDCA, DCA and ACA); not inducible by taurine- and glycine-amidated CDCA. [Isoform 4]: Promotes transcriptional activation of target genes ABCB11/BSEP (inducible by unconjugated CDCA, ACA and DCA), NR0B2/SHP (inducible by unconjugated CDCA, ACA and DCA), SLC51B/OSTB (inducible by unconjugated CDCA and DCA) and FABP6/IBAP; most efficient isoform compared to isoforms 1 to 3; not inducible by taurine- and glycine-amidated CDCA.
Synonyms: BAR; FXR; HRR1; RIP14; HRR-1; PFIC5
Tractability: Small molecule: an approved drug acts on it; a structure with a bound ligand is known; a high-quality ligand is known; it has a high-quality binding pocket; it belongs to a druggable protein family. PROTAC: UniProt records ubiquitination sites on it; a small molecule that binds it is known.
Target class: Nuclear hormone receptor subfamily 1; Nuclear receptor; Nuclear hormone receptor subfamily 1 group H; Nuclear hormone receptor subfamily 1 group H member 4; Transcription factor
Chemical probes: CHEMBL3335672, Nidufexor (high quality)
Safety:
Unwanted effects reported when the protein is acted on. In parentheses: how it was acted on, where the effect was seen, and who reports it.
Increased, Liver Steatosis (activation; source: AOP-Wiki)
Gene: Protein-coding gene on chromosome 12 (100,473,708 to 100,564,414, forward strand). Ensembl gene ENSG00000012504.
Subcellular location: Nucleus; Nucleus (Isoform 1); Nucleus (Isoform 2); Nucleus (Isoform 3); Nucleus (Isoform 4)
Subcellular location (Human Protein Atlas): Nuclear speckles; Nucleoplasm; Cytosol; Primary cilium tip
Pathways (Reactome):
Metabolism: Endogenous sterols; PPARA activates gene expression; Recycling of bile acids and salts; Synthesis of bile acids and bile salts; Synthesis of bile acids and bile salts via 27-hydroxycholesterol; Synthesis of bile acids and bile salts via 7alpha-hydroxycholesterol
Gene expression (Transcription): Nuclear Receptor transcription pathway
Metabolism of proteins: SUMOylation of intracellular receptors
Gene Ontology:
Molecular function: bile acid binding; bile acid nuclear receptor activity; chenodeoxycholic acid binding; DNA-binding transcription activator activity, RNA polymerase II-specific; nuclear receptor activity; protein binding; RNA polymerase II cis-regulatory region sequence-specific DNA binding; RNA polymerase II transcription regulatory region sequence-specific DNA binding; sequence-specific DNA binding; transcription coregulator binding; DNA-binding transcription factor activity; DNA-binding transcription factor activity, RNA polymerase II-specific; nuclear receptor binding; DNA binding; nuclear retinoid X receptor binding; zinc ion binding
Biological process: cellular response to bile acid; cellular response to fatty acid; intracellular triglyceride homeostasis; negative regulation of apoptotic process; negative regulation of canonical NF-kappaB signal transduction; negative regulation of tumor necrosis factor production; negative regulation of type II interferon production; negative regulation of very-low-density lipoprotein particle remodeling; nuclear receptor-mediated bile acid signaling pathway; positive regulation of DNA-templated transcription; positive regulation of interleukin-17 production; positive regulation of phosphatidic acid biosynthetic process; positive regulation of transcription by RNA polymerase II; regulation of insulin secretion involved in cellular response to glucose stimulus; regulation of low-density lipoprotein particle clearance; regulation of transcription by RNA polymerase II; urea cycle; bile acid and bile salt transport; cell differentiation; cholesterol homeostasis; intracellular glutamate homeostasis; intracellular receptor signaling pathway; negative regulation of inflammatory response; negative regulation of transcription by RNA polymerase II; regulation of bile acid biosynthetic process; and 19 more
Cellular component: euchromatin; nuclear speck; nucleoplasm; nucleus; receptor complex; chromatin; RNA polymerase II transcription regulator complex
Genetic constraint (gnomAD): Loss-of-function variants: 16 observed, 42.13 expected, observed/expected ratio (o/e) 0.38, 90% interval 0.26 to 0.58. The upper end of that interval is the gene's LOEUF score, 0.58, which puts it in group 2 of 6, group 1 being the genes least tolerant of losing a copy. Missense variants: 344 observed, 439.65 expected, observed/expected ratio (o/e) 0.78, 90% interval 0.72 to 0.86. Synonymous variants: 164 observed, 157.8 expected, observed/expected ratio (o/e) 1.04, 90% interval 0.91 to 1.18.
Homologues: Orthologues: chimpanzee NR1H4 (95% identical), macaque NR1H4 (94% identical), rabbit NR1H4 (92% identical), mouse Nr1h4 (90% identical), dog NR1H4 (90% identical), pig NR1H4 (89% identical), rat Nr1h4 (89% identical), guinea pig NR1H4 (84% identical), tropical clawed frog nr1h4 (64% identical), zebrafish nr1h4 (64% identical), Caenorhabditis elegans nhr-48 (19% identical), Drosophila melanogaster Hr96 (17% identical), and 179 more. Paralogues in human: NR1H3 (31% identical), NR1H2 (30% identical), VDR (25% identical), THRB (24% identical), NR1D2 (24% identical), NR1I2 (24% identical), RARA (24% identical), RARG (23% identical), RARB (23% identical), RORC (23% identical), NR1D1 (22% identical), NR1I3 (22% identical), and 6 more.
Diseases named in the same sentence as NR1H4 in open-access papers:
NR1H4 is named in the same sentence as 325 diseases in open-access papers, as found by Europe PMC text mining. Sharing a sentence is not in itself a finding about the gene and the disease. The quoted sentences say what the papers report.
Obesity (267 papers, 2011 to 2026). Accumulation of substantial excess body fat. "NR1H4 variants rs35724 and rs10860603 have been previously shown to be significantly associated with elevated body mass index and obesity." (PMID 22929053, 2012). "In addition, the farnesoid X receptor (FXR, encoded by Nr1h4) would regulate the homeostasis of BAs, lipids and glucose, which has been reported to have important role in obesity and hypercholesterolemia." (PMID 34899310, 2021). "It has been confirmed that FXR is required for gut-microbiota-induced obesity in Fxr- (also known as Nr1h4) null germ-free mice." (PMID 32034442, 2020).
cholestasis (231 papers, 2012 to 2026). Impairment of the bile flow caused by obstruction within the liver, or outside the liver in the bile duct system. "Consistently, combined loss of Nr1h4 and Nr0b2 in mice results in juvenile onset cholestasis that progresses to HCC." (PMID 41460563, 2025). "A recent study demonstrated that human NR1H4 mutations induce cholestasis and hepatocyte death by suppressing ABCB11 expression." (PMID 40499905, 2025). "Mutations and reduction in Nr1h4, and Nr0b2 transcript levels have been noted in cholestasis (reduced bile flow and subsequent increase in hepatic and serum bile acids [(BA])), fatty liver disease, and liver cancer." (PMID 41460563, 2025). "Whole-exome sequencing and single-nucleotide polymorphism (SNP) arrays of two unrelated probands with severe cholestasis revealed homozygous loss of function mutations in NR1H4, located at 12q23.1." (PMID 26888176, 2016). "Severe cholestasis was barely observed in young male mice with Nr1h4-deficiency." (PMID 40499905, 2025). "PFIC5, paediatric cholestasis with jaundice, low γGT, and elevated BAs, whose onset age ranges from a few days to a few weeks, is related to a deficiency of the BA receptor known as farnesoid X receptor (FXR) due to loss of function variant in the NR1H4 gene." (PMID 39984942, 2025). "Research suggest that RIF-induced liver injury, steatosis, and cholestasis are associated with farnesoid X receptor (FXR, encoded by the NR1H4 gene) dysfunction and altered bile acid (BA) metabolism, and that the JNK signaling pathway is partially implicated in this injury." (PMID 39512799, 2024). "NR1H4 is closely related to cholestasis, which can cause depression." (PMID 37433869, 2023). "Mutations in NR1H4 may lead to another phenotype of progressive intrahepatic cholestasis in children that has been referenced as PFIC5 previously, but are better described as cholestasis secondary to NR1H4 mutations." (PMID 32432119, 2020). "NR1H4 gene mutations cause PFIC5, while those in the MYO5B gene generate PFIC6 or MYO5B-related cholestasis." (PMID 39697951, 2024). "PFIC5 is a form of cholestasis that occurs in newborns and is caused by mutations in the nuclear receptor FXR/NR1H4." (PMID 37324459, 2023). "Farnesoid X receptor (FXR) is a nuclear receptor subfamily 1 group H member 4 (NR1H4) which has crucial regulatory functions in multiple biological processes including cholestasis and atherosclerosis." (PMID 32450881, 2020). "The nonresponsiveness of coagulopathy to vitamin K treatment is likely a direct consequence of the loss of FXR function, representing an important distinguishing diagnostic feature of NR1H4-related cholestasis." (PMID 30148122, 2018). "Interestingly, expression of NR1H4, which encodes FXR and is thought to play a role in macrophage inflammasome activation in cholestasis, is negligible across all macrophages." (PMID 33411796, 2021). "Overall, the development of early cholestasis and rapidly progressive hepatic dysfunction in humans with mutations in the NR1H4 gene reinforces the role of FXR as a master regulator of bile acid homeostasis, and confirms a key role in hepatoprotection by preventing bile acid-induced liver toxicity." (PMID 26888176, 2016). "In the cholestatic patients, an upregulation of the nuclear receptors NR1H4 (FXR) and NR1H3 (LXR) was observed in contrast to the observed downregulation in human PCLS, which could be due to the different causes of cholestasis or the large difference in time frame." (PMID 27344345, 2017). "Thus, our patient data, the direct role of FXR in regulating coagulation, and clinical studies in obeticholic acid treated patients and in other forms of cholestasis all suggest early onset, vitamin K-independent coagulopathy as a distinguishing diagnostic feature of NR1H4-reated cholestasis." (PMID 26888176, 2016).
cholestasis (continued). "For PPARα and NR1H4 expression we used liver biopsy dataset GSE65359 (84 cases of hepatitis B), fetal and adult liver sample dataset GSE61276 (106 cases), and cholestasis gene expression excluding BA." (PMID 36090996, 2022). "The bile acid-sensing nuclear receptors farnesoid X receptor (FXR; NR1H4) and PXR have been investigated in the rodent bile-duct ligation (BDL) model of cholestasis." (PMID 23240054, 2012). "The bile acid-activated farnesoid X receptor (FXR, NR1H4) has emerged as a promising therapeutic target as it orchestrates key processes that may counteract or at least ameliorate cholestasis." (PMID 37841639, 2023). "FXR, also known as NR1H4, can be activated by BA, especially CDCA, DCA, and LCA, and plays an important role in SULT2A1 expression in liver and a protective role in maternal cholestasis induced damage and oxidative stress." (PMID 31443432, 2019). "Taken together, these results imply that suppression of bile acid synthesis, vis-à-vis, reduced CYP7A1, is not sufficient to prevent cholestasis but that concurrent NR1H4-mediated activation of hepatobiliary bile acid efflux into the intestine is a primary molecular mechanism." (PMID 41043692, 2025). "In addition, Nr1h4/Shp double-KO mice, unlike Nr1h4 or Shp single-KO mice, developed severe cholestasis at an early stage, such as at three weeks of age." (PMID 40499905, 2025). "GSEA enrichment analysis results for high and low expression of PPARα and NR1H4 in BA patients, and GSEA results excluding patients with hepatitis B, normal liver, liver cancer, and non-BA cholestasis." (PMID 36090996, 2022).
Hepatic steatosis (201 papers, 2013 to 2026). Steatosis is a term used to denote lipid accumulation within hepatocytes. "From this approach, we identified strong enrichment of genes induced by B2D with metabolic transcription factor knockouts that cause fatty liver disease, such as Ppara, Nr1h4, and Nr0b2." (PMID 37417957, 2023). "The NR1H4 gene encodes the farnesoid X receptor (FXR), and its activation may have been involved in the reduction of liver steatosis and hyperlipidemia, through the suppression of de novo lipogenesis and the promotion of triglycerides oxidation and clearance." (PMID 30200543, 2018). "The top-ranked gene was NR1H4 (FXR) for which role/therapeutic target is clear in both cholestatic and fatty liver diseases." (PMID 39130146, 2023).
Insulin resistance (141 papers, 2010 to 2026). Increased resistance towards insulin, that is, diminished effectiveness of insulin in reducing blood glucose levels. "A remarkable and unexpected finding of our study is an inverse association between the methylation levels at the FXR/NR1H4 promoter and features of the MetSynd, including blood pressure, insulin resistance, and body weight gain during gestation." (PMID 24498169, 2014). "NR1H4 knockout mice manifested high serum TG and FFA levels, in association with impaired glucose tolerance and insulin resistance." (PMID 37396157, 2023).
liver fibrosis (128 papers, 2012 to 2026). "Of note, Nr1h4 (FXRα) suppresses liver fibrosis development, and its deficiency is associated with fatty liver and increased susceptibility to NASH in high fat diet-fed mice." (PMID 36711947, 2023). "NR1H4 deficiency has been associated with progressive intrahepatic cholestasis and subsequent hepatic fibrosis." (PMID 36768808, 2023). "The combination of the NR1H4 (FXR) agonist obeticholic acid and a ubiquitin-like inhibitor may significantly inhibit the activation of hepatic stellate cells and inhibit liver fibrosis." (PMID 36090996, 2022). "Activation of the TGFβ pathway is closely associated with low expression of PPARα and NR1H4, indicating that enhancing PPARα and NR1H4 levels may delay the progression of liver fibrosis." (PMID 36090996, 2022). "Nr1h4 (FXRα), a bile acid sensor that regulates hepatic bile acid metabolism 59, showed a liver cell type specificity similar to Ppara, except that its expression was high in hepatic stellate cells, which have a major role in the deposition of extracellular matrix during liver fibrosis." (PMID 36711947, 2023).